S100A4 (S100 calcium binding protein A4)
Diseases named in the same sentence as S100A4 in open-access papers (continued):
Sharing a sentence is not in itself a finding about the gene and the disease.
interstitial lung disease (3 papers, 2021 to 2024). A diverse group of lung diseases that affect the lung parenchyma. "Regarding IPF, S100A4 mRNA and protein levels have been found to significantly increase in BALF compared to controls and other interstitial lung diseases (ILDs), but also in lung tissue, as shown by immunohistochemistry studies." (PMID 37893169, 2023).
ischemia (3 papers, 2020 to 2022). A hypoperfusion of the BLOOD through an organ or tissue caused by a PATHOLOGIC CONSTRICTION or obstruction of its BLOOD VESSELS, or an absence of BLOOD CIRCULATION. "In addition, S100A4 was induced by acute ischemia and aortic stenosis and exerted pro-hypertrophic as well as cardio-protective effects." (PMID 35053115, 2022).
malignant glioma (3 papers, 2018 to 2022). A grade III or grade IV glioma arising from the central nervous system. "For example, it has been reported that neutrophils promote the malignant glioma phenotype through S100A4." (PMID 34827528, 2021).
metastatic melanoma (3 papers, 2010 to 2020). A melanoma that has spread from its primary site to another anatomic site. "Upregulation of S100A4 correlates with the upregulation of RAGE in metastatic melanoma cells in vitro, and elevated levels of S100A4 and RAGE are associated with high tumour burden in vivo." (PMID 32722137, 2020). "All these in vitro data were supported by studies using a mouse model of metastatic melanoma, where mice injected with S100A4 or RAGE overexpressing A375 cells showed higher tumor incidence and mortality than mice injected with the control non-transfected A375." (PMID 33256110, 2020).
papillary thyroid cancer (3 papers, 2005 to 2022). "To this end, we examined S100A4 gene expression in 6 benign multinodular goitres (MNG) and 28 matched samples of adjacent normal thyroid tissue (N), primary (T) and metastatic (M) papillary thyroid carcinomas (PTC) by immunohistochemistry and real-time RT–PCR analysis." (PMID 16265347, 2005).
Stroke (3 papers, 2013 to 2020). Sudden impairment of blood flow to a part of the brain due to occlusion or rupture of an artery to the brain. "Well-known members of DAMPs, including S100 family (e.g., S100a4, 8, 9) were induced, peaking at day 1 and/or 14 post-stroke." (PMID 32264906, 2020). "An increased expression of the newly identified stroke genes Il6ra, Il6st, S100a4, Stat1, and Stat2, but also the known genes Col1a1, Col1a2, Col3a1, has been implicated in blood vessel remodeling and contributes to vascular rarefaction, leakage, and intracranial aneurysms." (PMID 24672479, 2014).
thoracic aortic aneurysm (3 papers, 2013 to 2026). An aneurysm formed in the wall of the proximal portion of the descending aorta proceeding from the arch of the aorta. "On another hand, despite a previous study reported an increase of S100A4 levels in tissue and in serum of patients with thoracic aortic aneurysm, it could be due to the different mechanisms underlying the pathogenesis of abdominal and thoracic aneurysms development." (PMID 33919749, 2021). "This study investigated whether S100A4 plays a potential role in the formation of thoracic aortic aneurysm (TAA)." (PMID 23922901, 2013).
adenoma (2 papers, 2002 to 2021). A neoplasm arising from the epithelium. "Differences in the mRNA for S100A4 in the non-advanced adenoma group and the mRNA for S100A9 and S100A11 in the advanced adenoma group between men and women were confirmed." (PMID 33466593, 2021).
Alzheimer disease (2 papers, 2024 to 2025). A progressive, neurodegenerative disease characterized by loss of function and death of nerve cells in several areas of the brain leading to loss of cognitive function such as memory and language. "Of note, increased expression of S100B, S100A4, S100A6, S100A8, and S100A9 has also been linked with Alzheimer's disease." (PMID 38737767, 2024). "Therefore, we aim to investigate the specific effects of S100A4 in Alzheimer’s disease." (PMID 40787447, 2025).
aneurysm (2 papers, 2013 to 2019). Bulging or ballooning in an area of an artery secondary to arterial wall weakening. "Increased expression of S100A4 was observed in the αSMA-positive cells across the entire aortic wall of aneurysm samples, with the medial layer being more prominent than the intima and adventitia, results which resemble the findings in the animal model." (PMID 23922901, 2013). "Both autophagy factors also co‐localized with CD68+ cells and S100A4+ cells in murine aneurysm tissue; however, we chose not to further pursue these cell types in the in vitro analysis (data not shown)." (PMID 31025534, 2019).
atrial fibrillation (2 papers, 2021 to 2022). A disorder characterized by an electrocardiographic finding of a supraventricular arrhythmia characterized by the replacement of consistent P waves by rapid oscillations or fibrillatory waves that vary in size, shape and timing and are accompanied by an irregular ventricular response. "Many members of S100 family, including S100A8 and S100A9, have been involved in EMT in multiple types of cells: S100A4 was associated with expression of Snail in human cancers and atrial fibrillation." (PMID 34099591, 2021). "Therefore, the diagnostic efficacy of CYBB, CXCR2, and S100A4 in different populations and its role in the occurrence of atrial fibrillation still need more external validation." (PMID 35305619, 2022).
autoimmune thyroid disease (2 papers, 2012 to 2024). Inflammatory disease of the thyroid gland due to autoimmune responses leading to lymphocytic infiltration of the gland. "Tear S100A4 may serve as a biomarker for the propensity to develop thyroid eye disease (TED) in patients with autoimmune thyroid disease (AITD) before clinical manifestation and should be confirmed in future studies." (PMID 39359477, 2024).
bladder tumors (2 papers, 2012 to 2018). "In bladder tumors, overexpression of S100A4, S100A8 or S100A11, but not S100A9 in cancer tissues is associated with stage progression, invasion, metastasis and poor survival." (PMID 22838504, 2012).
bone metastasis (2 papers, 2015 to 2024). Transfer of a neoplasm from its primary site to bones. "Stromal podoplanin, S100A4, and PDGFRα expression was elevated in bone metastasis, while tumoral podoplanin and stromal PDGFRβ expression was elevated in lung metastasis." (PMID 26163388, 2015). "IL‐8 and S100A4 correlated with patient Gleason scores and bone metastasis." (PMID 39415352, 2024).
brain injuries (2 papers, 2018 to 2021). "To date, S100A4 could be included among the potential molecules capable of reducing or preventing neuronal damage, since synthetic peptides mimicking S100A4 exert neuroprotective effects in models of acute brain injuries." (PMID 33918416, 2021).
brain tumors (2 papers, 2008 to 2021). "S100A4 characterizes the properties of different brain tumors, representing both a promising biomarker and a potential target for their demise." (PMID 33918416, 2021). "Overall, S100A10 had the highest fold change between ependymoma and other brain tumours of three and S100A4 had the highest fold change between ependymoma and normal brain of 20.7." (PMID 18781180, 2008). "Furthermore, we highlight S100A4 as a gene involved in the pathogenesis of neurological disorders such as brain tumors, neurodegenerative diseases, and acute injuries." (PMID 33918416, 2021).
cataract (2 papers, 2021 to 2024). Partial or complete opacity of the crystalline lens of one or both eyes that decreases visual acuity and eventually results in blindness. "And Pde6b and Nrl were respectively identified as potential modifiers in Fox3e3 (-/-) and S100a4 (-/-) mice, expediting the progression of cataract development." (PMID 38439070, 2024). "Interestingly, lenses of older but not young S100A4−/− mice develop cataracts characterized by swelling of lens cortical fibers." (PMID 33500475, 2021).
chronic sinusitis (2 papers, 2022 to 2023). "S100A4 drives EMT in chronic sinusitis mucosal epithelial cells and accelerates nasal mucosa tissue remodeling." (PMID 37873538, 2023). "Since S100A4 is an effective inducer of CRS, it would be interesting to find out whether S100A4 is differentially expressed in different immune response types of sinusitis." (PMID 35154161, 2022).
Cirrhosis (2 papers, 2016 to 2024). A chronic disorder of the liver in which liver tissue becomes scarred and is partially replaced by regenerative nodules and fibrotic tissue resulting in loss of liver function. "The S100A4 expression of HPCs was firstly observed in mild hepatitis and increased significantly in moderate hepatitis, but decreased in severe hepatitis and cirrhosis." (PMID 27881141, 2016). "Noteworthy, only a few of HPCs in sections of severe inflammation and cirrhosis expressed S100A4 (n = 1.02 ± 0.44 per cm2 and n = 0.26 ± 0.17 per cm2)." (PMID 27881141, 2016).
dry eye syndrome (2 papers, 2012 to 2018). A syndrome characterized by dryness of the cornea and conjunctiva. "The protein S100A4 was also previously found to be upregulated in patients with dry eye syndrome." (PMID 22664934, 2012).
E. coli infection (2 papers, 2017 to 2025). "Here, upon infection with Citrobacter rodentium, a model for enteropathogenic Escherichia coli infection in humans, induced the infiltration of a large number of S100A4+ cells into the colon in wild type (WT) mice." (PMID 28935867, 2017). "Whether the molecular phenotype of prostate recruited myeloid cells (expression of Gli1, Lyz2, S100a4) and other markers changes over time, especially after resolution of E. coli infection, was not examined in this study." (PMID 39748675, 2025). "E. coli infection increased the proportion of RFP+ cells that co-express Ki67 in mice of Lyz2+ and Gli1+ cell lineages, but not in mice of Cd2+ and S100a4+ cell lineages." (PMID 39748675, 2025).
gastric adenocarcinoma (2 papers, 2022 to 2024). "We also investigated the impact of CAF markers highly clustered with COL1A1 and COL5A1 in correlation analysis, namely THBS2, FAP, INHBA, S100A4, COL11A1, or MMP11, on the outcome of CAF infiltration in stomach adenocarcinoma." (PMID 35739492, 2022). "Similarly, S100A4 was found to regulate cell migration but not cell proliferation in gastric adenocarcinoma." (PMID 38872805, 2024).
glomerulonephritis (2 papers, 2017 to 2023). A renal disorder characterized by damage in the glomeruli. "Whereas S100A8/9 and S100A12 are predominantly phagocyte-specific proteins, S100A4 (also known as fibroblast-specific protein 1 or metastasin) is more widely expressed and has demonstrated correlation with disease activity in various forms of glomerulonephritis." (PMID 29065913, 2017).
head and neck cancer (2 papers, 2016 to 2023). A primary or metastatic malignant neoplasm affecting the head and neck. "Previously, we have demonstrated that S100A4 play a crucial role in the maintenance of head and neck cancer-initiating cells (HN-CIC) population." (PMID 27793047, 2016). "Previously, we have demonstrated that S100A4 is required to sustain the head and neck cancer-initiating cells (HN-CICs) subpopulation." (PMID 27793047, 2016). "Consistently, using The Cancer Genome Atlas (TCGA) database, we observed a statistically significant positive correlation between the expression profiles of S100A4 and Nanog transcripts in head and neck cancer (p < 0.01)." (PMID 27793047, 2016). "We found that the mRNA expressions of S100A4 is significantly and positively correlated with Nanog in both sphere cells and head and neck cancers, consistent with our prior finding that demonstrates the co-expression of S100A4 and Nanog in HNSCC patients." (PMID 27793047, 2016). "Our previous study demonstrated that S100A4 is required to sustain the stemness and self-renewal property of the head and neck cancer-initiating cells (HN-CICs) population both in vitro and in vivo." (PMID 27793047, 2016).
Hepatitis (2 papers, 2016 to 2024). Inflammation of the liver. "The elevated mRNA levels of EpCAM, S100A4, Twist, or Snail were firstly confirmed in mild hepatitis and showed a positive relationship with inflammation severity." (PMID 27881141, 2016).
hidradenitis suppurativa (2 papers, 2021 to 2022). A chronic suppurative and cicatricial disease of the apocrine glands occurring chiefly in the axillae in women and in the groin and anal regions in men. "The S100A4 protein showed a statistically significant increase in concentration in plasma samples of hidradenitis suppurativa subjects compared to controls." (PMID 36235175, 2022). "The authors proposed S100A4 and S100A15 as novel serum biomarkers for monitoring hidradenitis suppurativa progression and suggested their role in the pathogenesis of the disease by promoting inflammation and fibrosis." (PMID 36235175, 2022).
hypertrophic cardiomyopathy (2 papers, 2018 to 2022). A condition in which the myocardium is hypertrophied without an obvious cause. "Methods and Results: S100A4 mRNA and protein levels were analyzed in different models of cardiac pathology via quantitative RT-PCR and Western blot, showing a higher S100A4 steady-state protein concentration in hearts of Mybpc3-knock-in (KI) hypertrophic cardiomyopathy (HCM) mice." (PMID 30283351, 2018).
infiltrating breast carcinoma (2 papers, 2008 to 2019). "Immune-histochemical analysis of 239 patient tissue samples revealed a correlation of higher CYR61 and S100A4 expression with invasive breast cancer and metastasis." (PMID 31709177, 2019). "This suggests that S100A4 is over expressed in infiltrating breast carcinoma compared to normal breast." (PMID 18771601, 2008). "CYR61 together with S100A4 might be utilized as therapeutic target and prognostic marker for invasive breast cancer and metastasis." (PMID 31709177, 2019).
infiltrating ductal carcinoma (2 papers, 2008 to 2019). "This study found that S100A4 was expressed in more cases of metastatic lymph node (35.1% cases) compared to matched infiltrating ductal carcinoma node positive (13.5% cases)." (PMID 18771601, 2008). "The majority (70%, 12/17) of paired samples showed that when there was a positive expression of S100A4 protein in metastatic lymph node, there was associated negative expression in the primary tumor (infiltrating ductal carcinoma) of the same patient." (PMID 18771601, 2008). "Positive expression of S100A4 was observed in 45.1% of the infiltrating ductal carcinoma node negative cases, while in infiltrating lobular carcinoma with node negative, the expression of S100A4 protein was observed in 48.8%." (PMID 18771601, 2008). "A positive expression of S100A4 was observed in 45.1% (55/122) cases of infiltrating ductal carcinoma node negative and 48.8% (20/41) cases of infiltrating lobular carcinoma node negative." (PMID 18771601, 2008). "This shows that S100A4 has a similar expression level in both infiltrating ductal carcinoma and infiltrating lobular carcinoma with node negative." (PMID 18771601, 2008). "S100A4 was absent in normal breast tissues while positive in 45.1% of infiltrating ductal carcinoma (IDC) node negative and 48.8% of infiltrating lobular carcinoma node negative." (PMID 18771601, 2008).
injury (2 papers, 2017 to 2018). Damage inflicted on the body as the direct or indirect result of an external force, with or without disruption of structural continuity. "In a previous study, mimicking S100A4-induced neuroprotection in vivo increased neuronal loss after traumatic brain injury and helped identify two neurotrophic motifs in the S100A4 sequence: H3 and H6." (PMID 29204268, 2017).
ischemic cardiomyopathy (2 papers, 2022 to 2025). Ischemic cardiomyopathy is a cardiomyopathy in which a weakness in the muscle of the heart due to inadequate oxygen delivery to the myocardium with coronary artery disease being the most common cause. "To elucidate the role of S100A4 in myocardial disease, particularly its impact on smooth muscle cell behavior in ischemic cardiomyopathy (ICM), we conducted rigorous in vitro experiments." (PMID 40717095, 2025).
laryngeal carcinoma (2 papers, 2012 to 2025). Carcinoma that arises from the laryngeal epithelium. "In laryngeal carcinoma cells, treatment with demethylating agents could induce expression of S100A4 at both RNA and protein levels." (PMID 22645613, 2012). "An example of hypomethylated genes in laryngeal carcinoma cells is S100A4." (PMID 22645613, 2012).
Lewis lung carcinoma (2 papers, 2004 to 2018). "Previously, S100A4 had been shown to correlate with the invasive ability in vitro of Lewis lung carcinoma cell lines." (PMID 14710237, 2004). "A significant linear correlation between S100A4 and cell motility, however, has only been previously demonstrated in the Lewis lung carcinoma cell system by measuring the phagocytic tracks of cells in the absence of a chemotactic stimuli." (PMID 14710237, 2004).
lymphoma (2 papers, 2013 to 2022). A malignant (clonal) proliferation of B- lymphocytes or T- lymphocytes which involves the lymph nodes, bone marrow and/or extranodal sites. "Moreover, Q compounds do not bind S100A4 (data not shown), which would argue for that, at least in the EL4 lymphoma model, the anti-tumor effect of OX is related to S100A9 binding." (PMID 23667563, 2013).
metastasis (2 papers, 2019 to 2023). The spread or migration of cancer cells from one part of the body (where they first appeared) to another. "In contrast, it has also been reported that S100A4 is associated with tumor differentiation, but not with lymph node metastasis and TNM stage." (PMID 31526392, 2019).
metastatic colorectal cancer (2 papers, 2011 to 2019). "The finding that niclosamide inhibits S100A4-driven metastasis triggers a phase II clinical trial (ClinicalTrial.gov registration number: NCT02519582) to evaluate its safety and efficacy in metastatic colorectal cancer." (PMID 31581665, 2019).
multiple sclerosis (2 papers, 2021 to 2025). A progressive autoimmune disorder affecting the central nervous system resulting in demyelination. "In multiple sclerosis, S100A4 overexpression promotes microglial polarization of pro-inflammatory type via the TLR4/NF-κB pathway, initiating neuroinflammation." (PMID 40787447, 2025). "A proinflammatory role of S100A4 was further demonstrated in multiple sclerosis, a demyelinating neurodegenerative disease characterized by strong inflammatory and immune responses." (PMID 33918416, 2021). "Moreover, S100A4 levels were found to be significantly increased in the cerebrospinal fluid of patients with multiple sclerosis compared to neurologic controls, suggesting a possible use of S100A4 as a biomarker for the disease." (PMID 33918416, 2021).
oral submucous fibrosis (2 papers, 2014 to 2023). "However, recent studies have linked S100A4 to some fibrotic diseases, and it is reported that S100A4 contributes to the pathogenesis of oral submucous fibrosis." (PMID 24885536, 2014).
pancreatitis (2 papers, 2009 to 2021). Inflammation of the pancreas. "Development of pancreatitis in Tgfbr2fspKO DC chimeras indicated that TGFβ signalling in S100A4-positive myeloid DCs is required to prevent development of mAIP and supports a role for TGFβ signalling in DC-mediated immune tolerance." (PMID 19625278, 2009). "S100A4+ DCs were implicated in the pathogenesis of AIP by demonstrating the presence of DCs that had undergone Cre-mediated Tgfbr2 recombination in pancreata from Tgfbr2fspKO mice, and by induction of pancreatitis in wild-type mice through transfer of DCs from Tgfbr2fspKO mice." (PMID 19625278, 2009).
peritonitis (2 papers, 2025). Inflammation of the peritoneum (tissue that lines the abdominal wall and covers most of the organs in the abdomen). "First, S100A4 has a direct role in regulating cell motility via interaction with myosin-IIA, and macrophages isolated from S100a4 -/- mice have impaired ability to migrate to inflammation sites in a thioglycolate-induced model of peritonitis." (PMID 40078995, 2025).